NSUN2 (NOP2/Sun RNA methyltransferase 2)
Diseases named in the same sentence as NSUN2 in open-access papers (continued):
Sharing a sentence is not in itself a finding about the gene and the disease.
ovarian carcinoma (continued). "We also assessed the effect of NSUN2 on E2F1 mRNA stability and found that NSUN2 depletion reduced the half-life of E2F1 mRNA in ovarian cancer cells, suggesting that NSUN2 promoted m5C modification of E2F1 mRNA and facilitated its stability." (PMID 38424195, 2024). "The protein level of NSUN2 was greatly increased in LUAD, LIHC, COAD, BRCA, HNSC, UCEC, pancreatic adenocarcinoma, ovarian cancer (OV), glioblastoma multiforme (GBM) and KIRC tissues vs. corresponding normal tissues." (PMID 37769000, 2023). "Furthermore, we analyzed the correlation between the expression of NSUN2 and E2F1 in ovarian cancer." (PMID 38424195, 2024). "NSUN2 protein expression was elevated in fresh ovarian cancer tissues compared with FTE tissues, and similar results were observed in two independent ovarian cancer cohorts in which protein expression in ovarian cancer and FTE tissues was evaluated 37,38." (PMID 38424195, 2024). "Like NSUN2, YBX1 was amplified in multiple cancers, including ovarian cancer." (PMID 38424195, 2024). "To further confirm that NSUN2-mediated m5C modification regulates E2F1 expression in a manner dependent on YBX1, we overexpressed NSUN2 in ovarian cancer cells with or without YBX1 expression and assessed the expression of E2F1." (PMID 38424195, 2024). "The study indicates that focusing on NSUN2 and E2F1 could be a potential treatment approach for ovarian cancer." (PMID 38424195, 2024). "NSUN2 is aberrantly upregulated in ovarian cancer and promotes the malignancy of ovarian cancer through regulating the expression of the oncogenic driver E2F transcription factor 1 (E2F1) in an m5C-dependent manner, and E2F1 facilitates the transcription of NSUN2 as well as MYBL2 and RAD54L." (PMID 38424195, 2024). "Despite the lack of significant differences in the NSUN2 RNA level among different grades of serous ovarian cancer, NSUN2 protein expression was increased in high-grade (grade 2 and grade 3) and advanced-stage ovarian cancer specimens." (PMID 38424195, 2024).
squamous cell carcinoma (10 papers, 2014 to 2023). A carcinoma arising from squamous epithelial cells. "Compared with normal human tissues and cells, the expression of NSUN2 is increased in a variety of tumor tissues, and NSUN2 is considered to be an effective prognostic marker for some cancers, such as squamous cell carcinomas and colon carcinomas." (PMID 34630524, 2021). "We observed esophageal atypical hyperplasia lesions or squamous cell carcinoma in Nsun2+/+ mice after 4-NQO withdrawal for 4 or 8 weeks." (PMID 34345012, 2021). "In squamous cell carcinoma, inhibition of m5C modification by down regulation of NSUN2 promotes cancer stem cell generation and tumorigenesis." (PMID 32194861, 2020). "In one study it has been shown that NSUN2 is over-expressed in tumors (benign papilloma and malignant squamous cell carcinoma) compared to normal cells." (PMID 32194861, 2020). "NSun2 is up-regulated in a wide range of cancers and knockdown of NSun2 in human squamous-cell-carcinoma xenografts decreased their growth." (PMID 25014650, 2014). "The m5C writer NSUN2 was demonstrated to enhance the progression of squamous cell carcinoma by stabilizing LIN28B-dependent GRB2, which could activate the AKT and RTK signaling pathways." (PMID 36246622, 2022). "Depletion of NSUN2 results in decreased growth of human squamous-cell-carcinoma xenografts, suggesting that NSUN2 could be potentially targeted for cancer therapy." (PMID 33376192, 2021). "However, recent studies reported that NSUN2 is correlated with survival in other types of squamous cell carcinomas." (PMID 32854705, 2020). "The growth of human squamous cell carcinoma xenografts was also inhibited by NSUN2 knockdown." (PMID 32978516, 2020).
pancreatic cancer (9 papers, 2022 to 2026). "Collectively, these findings demonstrated that NSUN2 lactylation enhances perineural invasion and tumor nerve interactions in pancreatic cancer models." (PMID 41356184, 2026). "To clarify the potential clinical implications of NSUN2 lactylation, we performed co-immunoprecipitation (Co-IP) followed by western blotting on protein extracts from pancreatic tumor tissues." (PMID 41356184, 2026). "NSUN2 silencing weakened the capability of proliferation, migration and invasion of pancreatic cancer cells." (PMID 40025166, 2025). "In pancreatic cancer (PC), NSUN2 is significantly upregulated in tumor tissues and is associated with invasive clinical features." (PMID 41256859, 2025). "Functionally, NSUN2 knockdown exerts a modest impact on pancreatic cancer cell growth and drug sensitivity, with effects becoming more pronounced over time." (PMID 40114967, 2025). "NSUN2 plays an enzymatic role in mediating m5C methylation enrichment in RNA within pancreatic cancer cells." (PMID 40370440, 2025). "In pancreatic cancer mouse models, NSUN2 expression is upregulated in cancer cells, and its knockdown slows the growth of pancreatic cancer spheroids." (PMID 40370440, 2025). "Knockdown of NSUN2 in pancreatic cancer cells significantly downregulates m5C methylation levels." (PMID 40370440, 2025). "The role of lactylation in regulating NSUN2 expression in pancreatic cancer remains unclear." (PMID 41356184, 2026). "In pancreatic cancer tissues, NSUN2 and ALYREF are significantly upregulated, with NSUN2 expression positively correlating with TNM stage and distant metastasis Elevated levels of NSUN2 and ALYREF are associated with shorter OS in patients with pancreatic cancer." (PMID 40114967, 2025). "Together, these results identify K692 as the critical lactylation site on NSUN2 that inhibits its ubiquitination, stabilizes the protein, and drives PNI in pancreatic cancer." (PMID 41356184, 2026). "Our findings highlight the potential of targeting NSUN2 lactylation and inhibiting m5C modification as promising strategies to prevent PNI and improve therapeutic outcomes in pancreatic cancer." (PMID 41356184, 2026). "Mechanistically, NSUN2-mediated m5C modification suppresses TIAM2 expression through YBX1, and disruption of the NSUN2/TIAM2 axis impairs the EMT, thereby slowing pancreatic cancer progression." (PMID 40114967, 2025). "Studies have revealed abnormal expression patterns of m5C methyltransferases, including NSUN2 and NSUN6, as well as m5C-binding proteins like YBX1 and ALYREF, in cancers such as esophageal, gastric, hepatocellular, colorectal, and pancreatic cancers." (PMID 40114967, 2025). "In contrast to previous studies, our research found that lactate does not upregulate the mRNA expression of NSUN2 in pancreatic cancer cells." (PMID 41356184, 2026). "Our study reveals that lactylation-induced NSUN2-mediated RNA m5C modification is a crucial driver of PNI in PDAC, highlighting NSUN2 inhibition as a novel and promising therapeutic strategy for addressing this aggressive feature of pancreatic cancer." (PMID 41356184, 2026).
viral infection (9 papers, 2023 to 2025). "As for viral infection regulation, NSUN2 has been reported not only to facilitate enterovirus 71 replication via m5C modification but also to interact with the viral‐encoded VP1 protein and maintain its stabilization in a m5C‐independent manner." (PMID 40156167, 2025). "In viral infections, NSUN2 assumes a pivotal role in regulating m5C methylation, influencing gene expression and viral replication." (PMID 39175875, 2024). "Our previous work revealed that NSUN2 serves as a negative regulator of type I interferon responses in antiviral innate immunity during various viral infections." (PMID 39110796, 2024). "NSUN2 negatively regulates IFN-I responses during multiple viral infections, including SARS-CoV-2 infection." (PMID 38715608, 2024). "Because NSUN2 is constitutively expressed in uninfected cells, in the early stage of viral infection, the level of NSUN2 is relatively abundant and enough to modify large amounts of the newborn SARS-CoV-2 RNAs." (PMID 39110796, 2024). "The results revealed that both viral infection and the core protein transfection led to a modest increase in NSUN2 mRNA level." (PMID 38048324, 2023). "Subsequently, we investigated the impact of the core protein transfection and viral infection on NSUN2 mRNA levels." (PMID 38048324, 2023). "In response to viral infection, NSUN2 downregulates the levels of specific ncRNAs and alters their m5C levels, which directly and indirectly modulates the type I interferon response mediated by the RIG-I signaling pathway and enhances the antiviral response." (PMID 37915585, 2023). "Similar mechanisms have been observed in Mouse Leukemia Virus (MLV) and Alphaviruses, where a diminished NSUN2 level can reduce viral infection through downregulating m5C modifications." (PMID 37915585, 2023). "Additionally, NSUN2 has been shown to be a negative regulator of type I IFN responses during viral infections by degrading IRF3 mRNA; its knockout or knockdown enhances IRF3 mRNA and protein levels, thereby amplifying IFN responses." (PMID 41059804, 2025). "However, in the late stages of viral infection, because of the decrease of NSUN2 caused by SARS-CoV-2 infection, there are fewer NSUN2 proteins in the cell, and large amounts of progeny viruses containing m5C modifications are released outside the cell." (PMID 39110796, 2024). "Besides, reduced NSUN2 expression is sufficient for maintaining HBV m5C to facilitate efficient viral infection." (PMID 39664561, 2024). "Knockout of NSUN2 can enhance type I interferon responses and downstream interferon-stimulated genes (ISGs) expression after some viral infections both in vitro and in vivo, thus inhibiting the replication of vesicular stomatitis virus (VSV), herpes simplex virus 1 (HSV-1), or Sendai virus (SeV)." (PMID 39110796, 2024). "Moreover, the regulatory role of NSUN2 in viral infection and host innate immune response was also highlighted." (PMID 38715608, 2024). "Moreover, NSUN2, a typical m5C methyltransferase, negatively regulates type I interferon responses during various viral infections, including SARS-CoV-2." (PMID 38035086, 2023). "Knockout of NSUN2 notably reduced m5C levels in SARS-CoV-2 virion RNA and increased viral infection." (PMID 39110796, 2024). "NSUN2 knockout or knockdown can enhance the expression of IFN-I and downstream ISGs during various viral infections in vitro." (PMID 38715608, 2024). "It serves as a negative regulator of interferon response by accelerating the fast turnover of IRF3 mRNA, while endogenous NSUN2 levels decrease during SARS-CoV-2 and various viral infections to boost antiviral responses for effective elimination of viruses." (PMID 38035086, 2023).
endometrial cancer (8 papers, 2022 to 2025). Primary or metastatic malignant neoplasm involving the endometrium (mucous membrane that lines the endometrial cavity). "NSUN2 is significantly upregulated in endometrial cancer due to epigenetic enhancement of H3K4me3 levels in the promoter region, which is triggered by KDM5A downregulation." (PMID 41462962, 2025). "For example, in endometrial cancer, NSUN2 increases m5C modifications on SLC7A11 mRNA, enhancing its stability and expression, reducing lipid peroxidation, and inhibiting ferroptosis." (PMID 41463199, 2025). "Another study showed that NSUN2 knockdown significantly increased the levels of lipid peroxides and lipid ROS in endometrial cancer cells, thereby enhancing the sensitivity of endometrial cancer to ferroptosis." (PMID 40821694, 2025). "NSUN2 enhances m5C modification of mRNA, promoting endometrial cancer cell proliferation." (PMID 41462962, 2025). "The NSUN2/SLC7A11 axis inhibits endometrial cancer (EC) growth by increasing ferroptosis, suggesting that NSUN2 may serve as a prognostic biomarker and therapeutic target for EC patients." (PMID 38654314, 2024). "In endometrial carcinoma, the expression levels of NSUN2 were similar to that in normal tissue, suggesting that NSUN2 might be dispensable for tumorigenesis in endometrial carcinoma." (PMID 35280737, 2022).
esophageal cancer (8 papers, 2020 to 2025). A primary or metastatic malignant neoplasm involving the esophagus. "NSUN2-methylated lncRNA (NMR) is significantly upregulated in esophageal cancer tissues and is associated with reduced overall survival." (PMID 40370440, 2025). "Another study suggested that NSUN2 has a high mutation rate in gastric and esophageal cancers and has more protein alteration sites." (PMID 35574373, 2022). "In esophageal cancer cells, NSUN2 was found to associate with and methylate an lncRNA, NMR (also known as LINC01672 or lnc-CAMTA1-1:2/CAMTA1-IT1), for which expression is associated with resistance to cisplatin or paclitaxel." (PMID 32708015, 2020). "In esophageal cancer, RNA m5C methylation is primarily mediated by NSUN2 and participates in the disease process by affecting cancer-related genes and pathways." (PMID 40370440, 2025). "In esophageal cancer cells, NSUN2 binds and methylates NMR (nucleotide metabolism regulator) lncRNA, whose expression associates with esophageal cancer resistance to cisplatin or paclitaxel." (PMID 36969033, 2023). "As reported, the m5C writer NSUN2 was proven to stabilize the GRB2 mRNA via m5C dependent manner in esophageal cancer." (PMID 35603206, 2022). "Alternatively, it may be possible to target NSUN2-mediated events such as that shown for the lncRNA NMR in esophageal cancer, whereby NSUN2-methylated NMR interacts with the chromatin remodeling factor Bromodomain PHD Finger Transcription Factor (BPTF) to regulate resistance to cisplatin." (PMID 32708015, 2020).
osteosarcoma (8 papers, 2019 to 2025). A usually aggressive malignant bone-forming mesenchymal neoplasm, predominantly affecting adolescents and young adults. "NSUN2 deficiency inhibited fatty acid metabolism and the proliferation, migration, and invasion of osteosarcoma." (PMID 38721006, 2024). "However, the functions and underlying molecular mechanisms of NSUN2-mediated m5C in osteosarcoma (OS) remain unclear." (PMID 36792587, 2023). "NSUN2 is highly expressed in osteosarcoma tissues and cells, and high NSUN2 expression indicates poor prognosis in patients with osteosarcoma." (PMID 41462962, 2025). "NSUN2 is markedly upregulated in osteosarcoma tissues and cell lines and correlates with poor patient prognosis." (PMID 41256859, 2025). "The critical role and molecular mechanisms of NSUN2 in osteosarcoma progression and metastasis have also been elucidated." (PMID 41256859, 2025). "Animal models have validated that the inhibition of the NSUN2/FABP5 axis attenuates the prooncogenic effects of m5C modification in osteosarcoma, thus presenting novel avenues for osteosarcoma treatment." (PMID 38721006, 2024). "The FAO inhibitor etomoxir and FABP5 deficiency have proven effective in counterbalancing the impact of NSUN2 upregulation on FA metabolism and the proliferation, migration, and invasion of osteosarcoma 143b cells." (PMID 38721006, 2024). "NSUN2 accelerated osteosarcoma development by increasing FABP5 mRNA stability through m5C modification." (PMID 39340806, 2024). "To corroborate these results, we have generated an NSUN2 CRISPR/Cas9 knock-out cell line using human U-2 osteosarcoma (U2OS) cell line (NSUN2 KO)." (PMID 31276587, 2019). "In order to provide further evidence for mitochondrial localization of NSUN2, an HA-tagged version of the NSUN2 protein (GenBank: NM_017755.6) was transiently expressed in human osteosarcoma cells." (PMID 31276587, 2019). "NSUN2 significantly promotes osteosarcoma cell metastasis and EMT." (PMID 41256859, 2025). "Moreover, the increased expression of the m5C eraser NSUN2 is correlated with an unfavorable prognosis in patients with osteosarcoma." (PMID 38721006, 2024). "NSUN2 upregulated FABP5 expression by increasing FABP5 mRNA stability, promoting fatty acid metabolism in osteosarcoma cells and facilitating osteosarcoma progression." (PMID 41462962, 2025). "NSUN2 stabilizes FABP5 mRNA by inducing m5C modification, further promoting fatty acid metabolism in osteosarcoma cells." (PMID 41462962, 2025).
leukemia (7 papers, 2018 to 2025). A malignant (clonal) hematologic disorder, involving hematopoietic stem cells and characterized by the presence of primitive or atypical myeloid or lymphoid cells in the bone marrow and the blood. "NSUN2 promotes leukemia cell proliferation, enhances xenograft growth, and confers resistance to ferroptosis." (PMID 41256859, 2025). "Recent studies reveal that NSUN2-mediated RNA m5C plays a pivotal role in chromatin regulation and leukemia progression." (PMID 41256859, 2025). "In leukemia cells, NSUN2 and NSUN1 alter the RNA transcription process as part of the RNA polymerase II extension complex (eRNAPII), causing cells to develop resistance to venetoclax." (PMID 36313732, 2022). "Upregulation of RNA:m5C and its writer proteins, especially NSUN1 and NSUN2, has been reported in a variety of solid tumors and leukemia and contributes to tumor cell proliferation, metastasis and drug resistance." (PMID 33922187, 2021). "In this regard, an inhibitor of DOT1L (pinometostat) has recently entered clinical trials in leukemia, and it may be possible to see if this agent also inhibits NSUN2." (PMID 32708015, 2020). "After knocking down NSUN1 or NSUN2 by siRNAs, venetoclax-resistant K1VR lineage leukemia cells resensitize to low doses of venetoclax." (PMID 36313732, 2022). "Our study demonstrated that RNA cytosine methyltransferase NOP2/NSUN1 and NSUN2 interact with BRD4 and the elongating form of RNAP (CTD-S2P) to form a transcriptionally active chromatin structure in leukemia cells." (PMID 33922187, 2021). "In contrast, siRNA knockdown of NSUN1 or NSUN2 significantly reduced both the NSUN1 and NSUN2 proteins, but had little effects on the hnRNPK/NSUN3/DNTM2 complex and total RNA-pol-II in the leukaemia cells." (PMID 29563491, 2018). "Mechanistically, NSUN2 stabilizes mRNAs of key enzymes in the serine/glycine biosynthesis pathway, including PHGDH and SHMT2, through m5C modification, enhancing metabolic activity and supporting leukemia cell proliferation." (PMID 41256859, 2025). "In the most recently published research article in Nature, it has been demonstrated for the first time that the TET2 regulates the chromatin structure and leukaemogenesis in stem cells and leukaemia cells via MBD6 (binds 5-methycytosine residues in RNA) and NSUN2 (a RNA methylase)." (PMID 39757230, 2025). "In contrast, no appreciable interactions between hnRNPK and NSUN1 or NSUN2 were detected in OCI-M2 leukaemia cells." (PMID 29563491, 2018).
lung adenocarcinoma (7 papers, 2020 to 2025). A carcinoma that arises from the lung and is characterized by the presence of malignant glandular epithelial cells. "Regarding m5C RNA modifications in NK cells, both resting and activated NK cells are correlated with positive outcomes in HNSCC, glioma and lung adenocarcinoma patients, with NSUN2 being the most closely associated m5C gene." (PMID 37325635, 2023). "In lung adenocarcinoma patients, ALYREF, together with NSUN2, promotes m5C modification of YAP (Yes-Associated Protein) mRNA in the 3’-UTR, thus increasing the stability of YAP mRNA and causing enhanced exosome secretion, tumor malignancy and drug resistance." (PMID 37325635, 2023). "In lung adenocarcinoma patients, NSUN2 and ALYREF were found to be oncogenic through interacting with YAP mRNA." (PMID 37325635, 2023). "In addition, NSUN2 and ALYREF promoted YAP m5C modification in its 3’-UTR regions, increasing mRNA stability in lung adenocarcinoma." (PMID 38331765, 2024). "Here, we validated that YAP expression was higher in lung adenocarcinoma (LUAD) tissues compared to adjacent normal tissues, and found that YAP m5C modification occurred in its 328–331 3′ UTR region under the promotion NSUN2 and ALYREF, and increased the stability of YAP mRNA." (PMID 36123390, 2023).